IGF1R (insulin like growth factor 1 receptor)
Diseases named in the same sentence as IGF1R in open-access papers (continued):
Sharing a sentence is not in itself a finding about the gene and the disease.
cancer (continued). "IGF1R hyperactivation could lead to the increase in ERK1/2 protein phosphorylation (10-fold and 2.6-fold in dysplastic and cancer tissue, respectively), compared with basal state." (PMID 29662006, 2018). "Since IRS-1 is required for IGF-1R stimulation of cell proliferation and IRS-2 is involved in cancer motility and metastasis, inhibition of their function or expression could be therapeutically exploited." (PMID 29152592, 2017). "We conducted in vitro studies in ER-positive and -negative cell lines in an attempt to dissect the different prognostic potential of IGF1R expression in ER-positive and –negative cancers." (PMID 29207959, 2017). "Instead, the phenomenon is reminiscent of drug‐tolerant persisters (DTPs), which constitute < 1% of drug‐naïve cell populations, become enriched following exposure to high concentrations of anti‐cancer drugs (> 100‐fold above IC50 values) for > 9 days, and have hyperactive IGF‐1R signaling." (PMID 28069687, 2017). "Not to forget, however, CRPCa patients with low metastatic IGF-1R expression had a shorter cancer-specific survival than patients with high IGF-1R expression, despite their suggested increase in immune cell activity." (PMID 28447314, 2017). "Biasing the IGF-1R away from ERK-activation could also have important implications in preventing ERK-dependent migration and invasion of highly malignant cancer cells." (PMID 28796787, 2017). "Moreover, it is thought that circulating IGF-1R can interact with the IGF-1R targeting antibodies and prevent their interaction with the IGF-1R on cancer cells." (PMID 29387053, 2017). "The prognostic relevance of IGF1R and AREG was assessed using a multivariate proportional hazards model adjusted for the following established clinical prognostic factors: treatment arm, gender, age, cancer stage, and histological type." (PMID 26884344, 2017). "Two results did not have significant effects of IGF-1R inhibitors in cancer therapies but indicating a detrimental trends in survival outcomes." (PMID 28427155, 2017). "Indeed, as part of the current focus of pharmacological research on the INSR/IGF1R pathway in the treatment of cancer, more than 100 clinical trials have already investigated INSR/IGF1R inhibition." (PMID 28882129, 2017). "Most genes from the “Pathways in cancer” (FLT3, IGF1R, DAPK2, PLD1 and MMP9) are inhibited due to the action of BE resulting in an anti-proliferative and pro-apoptotic action of the combined therapy, with the notable exception of the up-regulation of the apoptosis inhibitor BIRC3." (PMID 28359318, 2017). "We found six genes, ADIPOQ, DKK1, IGF1, IGF1R, IGF2, and PLAUR were shared by all the four cancers." (PMID 28676692, 2017). "Depending on their cellular context and expression levels, IR, IGF1R, EGFR, c-Met and uPAR promote malignancy also through cooperating with each other and may be promising candidates for an improved cancer therapy." (PMID 27502396, 2016). "There are accumulating evidences showing that targeting distinct multiple inhibitory epitopes on the IGF-1R and using a combination of competitive and allosteric antibodies may be more effective ways of affecting the IGF- 1R pathway in cancer." (PMID 28261624, 2016). "In various cancer models, NDGA has been demonstrated to promote apoptosis and inhibit proliferation by suppressing the activities of lipoxygenase (LOX), insulin-like growth factor 1 receptor (IGF-1R) and human epidermal growth factor receptor 2 (HER2/neu)." (PMID 27863391, 2016). "Therefore, to analyze the relative role of IGFBPs and IGF2R in cancer, we developed a mass-action kinetics model of the IGF network that incorporated IGF1, IGF2, IGF1R, IGF2R, and IGFBPs." (PMID 26861122, 2016). "In the current study, we identify a specific molecular interaction between EGFR and IGF-1R that may play a role in resistance to cetuximab, the leading anti-EGFR inhibitory agent in current clinical use for cancer therapy." (PMID 27716204, 2016).
cancer (continued). "Research and clinical studies have indicated that IGF-1R and its ligands, insulin-like growth factors 1 and 2 (IGF-1 and IGF-2) and insulin have crucial role in the development, maintenance and progression of cancer." (PMID 28261624, 2016). "Given that 15% of all cancers worldwide are tobacco-related, NNK activation of the IGF-1R pathway may also help us understand the biology of these cancers." (PMID 27666821, 2016). "Similarly, furin inhibition in carcinoma cells diminishes PDGF-A and IGF1R processing and abolishes stimulation of related signaling pathway." (PMID 27548722, 2016). "However, the therapeutic efficacy of IGF-1R inhibitors, mainly monoclonal antibodies (mAb) and tyrosine kinase inhibitors (TKI), has been modest in a variety of human cancers." (PMID 26515601, 2015). "Cancer cells can use this pathway as an additional or alternate mitogenic pathway to signaling via the type-1 IGF receptor (IGF-1R), and can provide a mechanism by which cancer cells can become resistant to treatments targeting the IGF-1R." (PMID 26217307, 2015). "The type 1 insulin-like growth factor receptor (IGF-1R) and its signaling components are required for the development of the malignant phenotype, and low IGF bioactivity protects against the development of clinical cancers." (PMID 26217584, 2015). "Since cancer stem cell growth may require switching on an EMT phenotype, it will be interesting to establish whether the IGF-1R and IR-A function differently in cooperation with adhesion signaling." (PMID 26191041, 2015). "Overall, our results could help to direct the future design of clinical trial to test anti-IGF-1R mAbs in SCLC and other cancers." (PMID 26287334, 2015). "Furthermore, IR can form hybrid receptors with IGF-1R: IGF-1R/IRB has higher affinity for IGF-1 whereas IGF-1R/IRA has higher affinity for IGF-2 and is involved in cancer signaling pathways." (PMID 25743390, 2015). "IGF-1R signaling at focal adhesion complexes and its interplay with adhesion/cytoskeleton signaling has a critical role in cellular transformation, EMT, therapy resistance, and the plasticity of cancer cells." (PMID 26191041, 2015). "Because the EMT process can be regulated by a diverse array of cytokines and growth factors, we analyzed the activation status of several kinases and their effectors involved in cancer cell proliferation and survival, including EGFR, IGF-1R, Src, FAK, Akt, Erk1/2, mTOR, MEK1/2, and p70S6K." (PMID 26416450, 2015). "Because the IGF-1R/Akt pathway is a common upstream regulator of p70S6K, HIF-1α, and COX-2, we hypothesized that glucosamine inhibits cancer cell proliferation through this pathway." (PMID 24438088, 2014). "Numerous reviews on the role of the IGF-1R/IRS-1 axis and its role in cancer are available." (PMID 25533015, 2014). "Overexpression of IGF1R and INSRA increased colony formation of cancer cells." (PMID 24809298, 2014). "Western blot analysis confirmed that the two cancer cell lines expressed IGF-1R, with levels not notably affected by glucose concentration." (PMID 24396438, 2014). "IGF-1R can be founded in most solid tumors and hematological malignancies examined to date, and IGF-2 overexpression, IGFBP modulations, and IGF-2R down-regulation have also been founded in cancer cells." (PMID 25424625, 2014). "IGF-1R represents a potential target for cancer treatment since is not essential for normal cell survival." (PMID 24709958, 2014). "Vice versa downregulation of either IGF1R or total INSR decreased cancer cell proliferation while increasing proliferation in non-cancerous cell lines." (PMID 24809298, 2014). "The findings of the present study provide evidence supporting the value of glucosamine as an effective and non-toxic IGF-1R blocking agent for cancer therapeutics." (PMID 24438088, 2014). "Notably, by targeting both IR and IGF-1R, PTB-U-box was able to suppress glucose metabolism of cancer cells." (PMID 24970814, 2014).
cancer (continued). "Although IGF-1R and IR are both widely expressed on normal tissues, the strong implications of IGF-1R in various cancers have already been well recognized and therapeutic strategies with antibodies and small molecule TKIs have been actively tested in clinical trials." (PMID 24970814, 2014). "High IGF1R expression levels and elevated circulating IGF1 levels have been demonstrated to be correlated with improved response to IGF1R-targeted therapies in clinical trials of malignant tumors." (PMID 25289085, 2014). "Such qualities are often a characteristic of trophic membrane receptor complexes like EGFR, HER2/neu, IGF-1R, and VEGFR that are each over-expressed by several neoplastic cell types including adenocarcinomas and carcinomas that affect the breast, ovary, prostate, lung and intestine." (PMID 25844392, 2014). "Invasive cancer showed pooled expression rates of 35% for CAIX (95% confidence interval (CI): 26-46%), 51% for GLUT1 (CI: 40-61%), 46% for CXCR4 (CI: 33-59%), and 46% for IGF1R (CI: 35-70%)." (PMID 24206539, 2013). "Additionally, amino acid deprivation enhanced HuR binding to IGF-1R mRNA and reduced IRES activity, while mitotic block by nocodazole lowered HuR binding and enhanced IRES activity in cancer cells." (PMID 24051403, 2013). "Importantly, target genes involved in epithelium development (RGMA, SHANK3, PAX6, PFN1, WNT4) and cancer (CBL, CYCS, FGF7, IGF1R, PTEN, PIK3CD, WNT4) address to a further role in the onset of epithelial abnormalities and oncogenesis." (PMID 23936163, 2013). "The IGF-1R inhibitor, PPP, is currently in clinical trials for the treatment of human cancers." (PMID 24182354, 2013). "IGF-1R expression was evaluated by determining the percentage of cells with cytoplasmic IGF-1R in HPV-positive/negative cancer." (PMID 23708675, 2013). "Over-expression of both IGF-1R and INSR in cancer cells leads to an over-expression of Hybrid-R as well; however, the mechanisms that regulate Hybrid-R formation are currently unknown." (PMID 22879999, 2012). "Approaches leading to overall suppression of IGF-1R are needed rather than the agents blocking its thymidine kinase activity for providing better anti-cancer efficacies." (PMID 22792362, 2012). "When adding CD44v6 to the panel, 80.1% of all cancers could be ‘detected’ with at least one marker in a panel consisting of HER2, GLUT1, EGFR, IGF1-R, and CD44v6." (PMID 22695343, 2012). "In cancers such as adenocortical carcinoma and HCC, where insulin receptor binds to IGF ligands with higher affinity, OSI-996 is able to inhibit both insulin receptor and IGF-1R to achieve maximum inhibition of the IGF axis." (PMID 21729319, 2011). "Moreover, IGF-1R has been shown to upregulate Cox-2 mRNA expression and PGE2 synthesis in cancer cells." (PMID 21813027, 2011). "In the mouse skin model, IGF-1 mRNA levels are elevated consistently in papillomas and carcinomas, while IGF-1R mRNA is up-regulated in some but not all tumors, mostly carcinomas." (PMID 21297902, 2010). "IGF1R interference in these epithelial plastic cancer cells did not affect the cSCC growth rate." (PMID 39075581, 2024). "A review of ongoing oncological trials suggests that IGF-1R blockers are no longer used in cancer." (PMID 39638246, 2024). "Targeting IGF-1R individually without IR could lead to rescue mechanisms for insulin, leading to cancer advancement within unsuccessful clinical trials." (PMID 39335147, 2024). "In summary, our findings demonstrate that cell context-dependent ITGB1 adhesion signals dictate IGF-1R subcellular localization and are required for IGF-1R internalization, Tyr1250/1251 phosphorylation, and receptor signaling outputs that support migratory and aggressive cancer phenotypes." (PMID 39608716, 2024).
cancer (continued). "IGF1R inhibitors Picropodophyllin (PPP) and Linsitinib can inhibit autophagy in human triple-negative breast cancer and improve the efficacy of chemotherapy immunotherapy in mice, which is a new strategy for cancer treatment in the context of chemical immunotherapy." (PMID 39404930, 2024). "Remarkably, our study unexpectedly discovered that KRAS G12C–mutant cancer cells, whether they exhibit intrinsic or acquired resistance to KRAS G12C inhibitors, also display cross-resistance to other inhibitors targeting EGFR, IGF1R, MEK, or SHP2." (PMID 39704172, 2024). "In this study, we observed that cancer cells resistant to KRAS G12C inhibitors also display cross-resistance to other targeted therapies such as inhibitors of epidermal growth factor receptor (EGFR), insulin-like growth factor 1 receptor (IGF1R), MEK, PI3K, or SHP2." (PMID 39704172, 2024). "This may contribute to the lack of efficacy of cell surface-targeted IGF-1R antibodies in cancers versus thyroid eye disease." (PMID 39608716, 2024). "Additionally, western blot and RT-qPCR analysis confirmed the positive regulation of CBX7 and IGF-1R on cancer stem cell markers CD133 and CD44, rescuing the negative influence of FOXC1 knockdown on these markers." (PMID 38413558, 2024). "Furthermore, targeting the IR/IGF1R axis in TNBC failed to produce robust inhibition of cancer cell lines in vitro." (PMID 36920947, 2023). "Despite many studies supporting the role of IGF1R in tumorigenesis, clinical trials targeting its activity have not been successful, indicating that IGF1R might not be the key oncogenic driver in these cancers." (PMID 37686528, 2023). "In addition, INSR and IGF1R are important for energy metabolism, cell growth, and cancer progression, and to our knowledge, no quantitative data have been published for INSR." (PMID 36890818, 2023). "In addition, the expression levels of IGF-1R and INSR are predictive of cancer outcome." (PMID 36755926, 2023). "Notably, of the eight cancer-related genes, six (TSC1, TSC2, PIK3CA, IGF1R, PDPK1 and AKT2) are known longevity related genes according to GenAge database in human/model organisms, and genetic manipulation of these genes can directly lead to shortening or extending lifespan of model organisms." (PMID 37582720, 2023). "Notably, in some benign and malignant tumors, IGF2 expression is directly regulated by Pleomorphic adenoma gene 1 (PLAG1), inducing autocrine IGF-1R signaling that leads to the activation of PI3K/AKT downstream cascade, enhancing cell survival and proliferation." (PMID 36901760, 2023). "No other small molecule inhibitors of IGF-1R remain in cancer clinical trials." (PMID 37858153, 2023). "Given the positive association between nuclear IGF-1R and DDT, it is not surprising that higher levels of nuclear IGF-1R have recently been correlated with lower levels of endogenous replication stress in cancer cells." (PMID 37858153, 2023). "One possible reason for the resistance of cancer cells to IGF-1R inhibitors is the compensatory activation of RTK signaling; therefore, several combination therapies have recently emerged to improve efficacy, such as IGF-1R inhibitors in combination with other RTK inhibitors." (PMID 36755926, 2023). "Consequently, numerous therapeutic strategies have been developed to inhibit or prevent the activation of the IGF signaling pathway in cancer cells, primarily through IGF-1R blocking antibodies and tyrosine kinase inhibitors that impede the tyrosine kinase domains of IGF-1R and IR." (PMID 38203494, 2023). "Elevated KLHDC8A expression was associated with sensitivity as measured by AUC with an Aurora B/C kinase inhibitor, a JMJD3 inhibitor, a pan-cancer inhibitor (BRD-4132) with unknown molecular targets, and an insulin-like growth factor 1 receptor (IGF1R) inhibitor." (PMID 36394953, 2023).
cancer (continued). "Additionally, the combined targeted therapy, including targeted agents (which were against EGFR, ALK, BRAF, IGF-1R, MET(c-MET), VEGF) and antibody–drug conjugate (ADC), as well as cancer vaccines, was among the top three most effective treatment interventions in this study." (PMID 36361201, 2022). "However, IGF1R inhibitor AEW-541 rescued all AV-treated cells and VHI-treated PANC-1 and T24 (VHI-sensitive) cells, suggesting that the VHI anti-cancer mechanism may be part of AV’s effect." (PMID 36497315, 2022). "Furthermore, the mRNA levels of cancer factors including heat shock protein 90 alpha family class B member 1 (HSP90AB1), MYC, and insulin like growth factor 1 receptor (IGF1R) were analyzed by quantitative real-time PCR assay to explore the possible antitumor mechanisms of ME." (PMID 36362498, 2022). "Nonetheless, in other cancer patients, anti-IGF-1R mAb have no significant therapeutic effect." (PMID 35680570, 2022). "Thus, IGF-1R may provide a useful therapeutic target for alleviation of SCC and other cancers 14, 17-23." (PMID 35401828, 2022). "ITGB3-+ IGF1R-targeting drugs (cilengitide + linsitinib) could be used as an effective therapy for suppressing the adaptive formation of the HDGF-LGR5 protein complex, which enhanced cancer stemness during MAPKi stress." (PMID 34106558, 2021). "This research comprehensively analyzed the expression pattern of IGF-1 and IGF-1R and the influence of IGF-1 and IGF-1R on clinical significance in prognosis prediction among 33 types of malignancies using The Cancer Genome Atlas (TCGA) and the Cancer Cell Line Encyclopedia (CCLE) databases." (PMID 34804946, 2021). "We demonstrate that GR activation induces cancer cell dormancy, accompanied by a diminished response to a large array of anticancer drugs, activation of growth factor survival signalling (IGF-1R) and acquisition of vulnerability to IGF-1R inhibitors in cell lines and xenograft models." (PMID 34272384, 2021). "Thus, cancer cells adapt very rapidly to PI3K inhibition, mainly due to feedback signals leading to activation or enhanced expression of growth factor receptors, such as IR/IRS1/IGF-1R, which, in turn, reactivate PI3K." (PMID 34638901, 2021). "Interestingly, we found that PKM2 depletion reduced IGF-1R protein level in various cancer cell lines, including A549, H1299, and H23 cells, without affecting the mRNA expression of IGF-1R." (PMID 34359752, 2021). "Furthermore, trastuzumab-resistant cancer cells might be the best candidates for anti-HER2 and anti-IGF-1R combined therapies." (PMID 33829018, 2021). "In addition, IL-6 treatment induced IGF-1 secretion and IGF-1R expression in NANOG/OCT4-HCC cell lines in a dose-dependent manner, suggesting crosstalk between IL-6/STAT3 signaling and IGF/IGF-1R signaling in HCC cancer stem cells." (PMID 33669204, 2021). "However, alternative receptor tyrosine kinases (EGFR, MET, HER2), post-translational processes (such as SUMOylation), IGF1R-EMT-independent pathways, and cancer–cell microenvironment interactions suggest that current preclinical models do not fully recapitulate the complex clinical scenario." (PMID 34065119, 2021). "In addition to the regulation of AKT and MAPK signaling, which could directly or indirectly impact various aspects of cell metabolism, recent studies indicate that the IGF-1R can directly interact with and phosphorylate PCNA in some cancer cell lines." (PMID 33753168, 2021). "In addition, in the field of cancer research, β-arrestin-biased agonism was also claimed to mediate insulin-like growth factor 1 receptor (IGF-1R) degradation and cell sensitivity to the anti-IGF-1R antibody, providing a new direction for cancer therapy." (PMID 34831211, 2021). "Targeted therapy against proteins facilitating IGF-1R location and activity in the Golgi or the nucleus, or enhancing IGF-1R sorting toward proteosomal degradation may be beneficial in certain subtypes of cancer." (PMID 33584548, 2020).